PRL (prolactin)
Diseases named in the same sentence as PRL in open-access papers (continued):
Sharing a sentence is not in itself a finding about the gene and the disease.
hyperprolactinemia (continued). "Hormonal evaluation revealed an extreme hyperprolactinemia (PRL = 10 610 mIU/L) almost exclusively due to macroprolactin isoform (MPRL = 10 107 mIU/L; recovery after PEG precipitation 4.7%) and hypogonadotropic hypogonadism." (PMID 23401806, 2013). "The specific search terms for diabetes, hyperlipidemia, obesity and hyperprolactinemia were “diabetes”, “hyperlipidemia” or “dyslipidemias”, “obesity” or “obese” or “overweight”, “hyperprolactinemia” or “prolactinoma” or “prolactin” respectively." (PMID 24355592, 2013). "Macroprolactinemia is a state of hyperprolactinemia characterized by predominant presence of the high-molecular PRL isoform in the circulation which has been considered biologically nonactive." (PMID 23401806, 2013). "Our meta-analysis indicated that adjunctive aripiprazole significantly lowered prolactin level in patients with antipsychotic-induced hyperprolactinemia." (PMID 23936389, 2013). "Prolactin levels were also significantly decreased by 62.3 ng/mL (95% CI, -76.7 to -47.9; p < 0.0001) in those patients who had switched due to hyperprolactinaemia (n = 39)." (PMID 24359635, 2013). "Hyperprolactinemia and presence of intracellular PRL and PRL-R have been detected by immunohistochemistry in different types of CNS tumors." (PMID 23317095, 2013). "The mean prolactin levels were 51.36 and 10.84 ng/ml among those with hyperprolactinemia and a normal prolactin level, respectively." (PMID 24312671, 2013). "PRL seems to be markedly increased in serum along aging (hyperprolactinemia), GH secretion declines during normal aging, resulting in lower serum levels of IGF1, and very disparate results have been reported with regard to Igbp-1." (PMID 23301049, 2013). "Our results provide evidence to support the use of dopamine agonists in reducing prolactin levels and persistent hyperprolactinemia, with cabergoline proving more efficacious than bromocriptine." (PMID 22828169, 2012). "Hyperprolactinemia frequently seen in macroprolactinemic patients is due to the delayed clearance of autoantibody-bound PRL." (PMID 23304187, 2012). "In suspect of the dopaminergic effect of risperidone to cause hyperprolactinemia and IGM, the prescription was shifted to prolactin-sparing second line agent (clozapine)." (PMID 22221904, 2012). "For patients with elevated prolactin concentrations, the practitioners are apt to query for presence of clinical symptoms related to hyperprolactinemia." (PMID 22455454, 2012). "The increase in serum PRL concentrations (hyperprolactinemia) often develops symptoms such as amenorrhea and galactorrhea in women and impotence in men." (PMID 23304187, 2012). "This was confirmed by the animal experiments showing that anti-PRL autoantibody-bound PRL was cleared from the rat circulation more slowly than monomeric PRL and that hyperprolactinemia developed in animal model of macroprolactinemia." (PMID 23304187, 2012). "When rats are immunized with rat pituitary PRL, anti-PRL autoantibodies are produced and hyperprolactinemia develops, mimicking macroprolactinemia in humans." (PMID 23304187, 2012). "Another 18 had a report of a clinical symptom potentially related to prolactin (five of whom also had a report of hyperprolactinemia)." (PMID 22676070, 2012). "Therapy is recommended for patients with drug-induced hyperprolactinemia, and these patients are usually shifted to a prolactin-sparing agent." (PMID 22221904, 2012). "Patients with hyperprolactinemia due to antipsychotic medication tended to have lower levels of prolactin compared to those with microadenoma, but the difference was not significant." (PMID 21750634, 2011). "Our patient had a normal PRL level but showed a response pattern suggestive of latent hyperprolactinemia following stimulation with TRH." (PMID 22152284, 2011).
hyperprolactinemia (continued). "Individuals with secondary causes of hyperprolactinemia (HPRL) were excluded; demographic, biometric, and clinical data, PRL levels, antiphospholipid antibodies, inflammatory markers, and other routine laboratory findings were analyzed." (PMID 21603198, 2011). "Low BMD values and hypogonadism were reported in young schizophrenic women with hyperprolactinemia who were treated with prolactin-raising antipsychotics." (PMID 20163720, 2010). "In their work, BMD values were similar in the hyperprolactinemia and normal prolactin level subjects both at the lumbar and femoral neck region." (PMID 20163720, 2010). "Meaningful interdependence was addressed in these analyses by the exclusion of observations with evidence of pre-existing hyperprolactinemia, potentially prolactin-related symptoms and pituitary tumor." (PMID 19210771, 2009). "Consensus recommendations propose that prolactin levels should be measured if signs and symptoms, elicited through a careful and thorough patient history, suggest hyperprolactinemia." (PMID 19210771, 2009). "Results of our study indeed suggest that clinicians are more likely to test prolactin levels in risperidone-treated patients, resulting in more hyperprolactinemia diagnoses and a larger pool of candidates for pituitary tumor investigation." (PMID 19210771, 2009). "Consistent with the more frequent diagnosis of hyperprolactinemia was the more frequent prolactin testing among risperidone-treated patients." (PMID 19210771, 2009). "Low BMD values and hypogonadism was reported in young schizophrenic women with hyperprolactinemia who were treated with prolactin-raising antipsychotics." (PMID 19118498, 2009). "Hyperprolactinemia is attributed to stalk compression; the degree of hyperprolactinemia is important for the differential diagnosis, because PRL levels above 200 ng/ml (9.0 nmol/liter) are generally considered to be indicative of a prolactinoma." (PMID 20062782, 2009). "Treatment of hyperprolactinemia/prolactinoma is via suppression of prolactin, either with medical therapy using dopamine agonists (eg bromocriptine or cabergoline) or transsphenoidal surgery." (PMID 18638386, 2008). "Normalizing elevated prolactin levels by using bisphosphonates in treating Paget's disease appears to be more appropriate than traditional treatment for hyperprolactinemia." (PMID 18638386, 2008). "Agonist treatment also blocked the increase in serum PRL concentration induced by the dopamine receptor antagonist haloperidol as well as hyperprolactinemia obtained by transplantation of the pituitary under the kidney capsule." (PMID 18081553, 2008). "The response to treatment of hyperprolactinemia/prolactinoma is via measurement of normalizing prolactin, along with subjective improvement of symptoms, such as return of libido or erectile function." (PMID 18638386, 2008). "During chronic administration of goserelin the mean PRL levels were similar to that in healthy control rats, in this way previous metoclopramide-induced hyperprolactinemia and by tumour presence, PRL expression was inhibited." (PMID 18045456, 2007). "First, adequate medical history, physical examination and routine laboratory testing should be employed to ascertain the presence of galactorrhea and document hyperprolactinemia by measuring serum PRL level." (PMID 23675050, 2007). "Thirty-four patients (35%, all macroadenomas) showed mild hyperprolactinaemia at the beginning of the study; of these, seven (7%) normalized their prolactin while on treatment with octreotide LAR." (PMID 17465997, 2007). "Withdrawal of a first-generation antipsychotic, or switching from a first-generation to a prolactin-sparing second-generation antipsychotic, should be done if hyperprolactinemia is present." (PMID 17262163, 2006). "The main source of PRL is the pituitary gland, but in recent years, some studies have reported hyperprolactinemia in patients with breast, lung, prostate and ovary tumours." (PMID 15617576, 2004).
hyperprolactinemia (continued). "Basal serum Zn++levels and serum PRL response toacute and chronic oral Zn++ administration were evaluated in seven patients with prolactinomasand one with idiopathic hyperprolactinemia." (PMID 18472906, 1999). "Because mild hyperprolactinemia may persist due to physiological processes or comedication or because prolactin levels may be uninterpretable (eg, during pregnancy), we emphasize the need for a patient-centered definition to describe this group." (PMID 41017446, 2026). "Furthermore, although rare in modern assays, high-dose hook effects lead to falsely normalized or slightly elevated prolactin measurements in extreme hyperprolactinemia by saturating assay antibodies." (PMID 41017446, 2026). "This study examined whether vitamin D status modifies the effects of this agent on prolactin and other anterior pituitary hormones in men with iatrogenic hyperprolactinemia." (PMID 41978113, 2026). "Of the 24 patients with PRL data obtained, hyperprolactinemia was present in 20 patients (83.3%)." (PMID 41001015, 2025). "Hormone therapy can also normalize sexual desire, satisfaction, and pain in women with hypothyroidism, as prolactin levels are likely to be higher in patients with hypothyroidism, and hyperprolactinemia can lead to decreased sexual desire and erectile dysfunction." (PMID 40003383, 2025). "However, even if complete remission is not achieved, surgery can lead to a clinically significant reduction in prolactin levels, such that lower doses of DA can be used to control hyperprolactinemia." (PMID 40004619, 2025). "Also, hyperprolactinemia’s consequences like osteoporosis can differ: prolonged prolactin elevation leads to hypogonadism in both sexes, contributing to reduced bone density." (PMID 40589655, 2025). "Furthermore, the tuberoinfundibular pathway also secretes dopamine to inhibit prolactin secretion; through a feedback mechanism, hyperprolactinaemia can directly enhance dopamine levels." (PMID 40896214, 2025). "In high-producing breeds, hyperprolactinemia may prioritize milk synthesis over metabolic recovery, while in Simmental cows, lower PRL signaling likely allows a more harmonized regulation of lipogenesis, lipolysis, and leptin expression." (PMID 41373870, 2025). "Among the first-generation antipsychotic agents (FGAs) in clinical use, the phenothiazines, butyrophenones, and thioxanthenes are related to movement disorders and hyperprolactinemia, while the substituted benzo amides are potent inducers of prolactin secretion, thus impacting lactation." (PMID 40732299, 2025). "As this phenomenon is more commonly reported in those with kidney disease, one hypothesis suggests PPIs impair renal prolactin clearance resulting in hyperprolactinemia and subsequent galactorrhea." (PMID 40271284, 2025). "Dopamine receptor agonists such as cabergoline, used to treat hyperprolactinemia, have shown beneficial effects in prolactin‐related headache and may reduce migraine burden." (PMID 41052788, 2025). "Persistent potential adverse reactions associated with paliperidone palmitate included weight gain, elevated prolactin levels, psychotic disorders, galactorrhea, amenorrhea, akathisia, extrapyramidal disorders, suicidal ideation, hyperprolactinemia, and erectile dysfunction." (PMID 39833706, 2025). "The features of hyperprolactinemia can occur either due to the impact of hypogonadism (due to inhibition of pulsatile gonadotropin-releasing hormone (GnRH) secondary to hyperprolactinemia) or from the primary effects of elevated prolactin." (PMID 40004619, 2025). "Hyperprolactinemia, characterized by elevated prolactin levels, may share overlapping features with PCOS and complicate diagnosis." (PMID 41510476, 2025). "The association of prolactin with NT-proBNP suggests that therapy reducing prolactin levels may decrease NT-proBNP and could be beneficial in heart failure patients with hyperprolactinemia and CKD." (PMID 40650124, 2025).
hyperprolactinemia (continued). "Prolactin abnormalities may be seen, either hyperprolactinemia due to stalk effect or hypoprolactinemia from pituitary damage." (PMID 41431507, 2025). "Hyperprolactinemia is defined as serum prolactin levels exceeding 25 ng/mL." (PMID 40535391, 2025). "Meanwhile, our findings demonstrate that patients with PRL dysregulation present significantly larger breast lesions, with a positive correlation observed between PRL levels and lesion dimensions, reinforcing the pathophysiological link between hyperprolactinemia and disease severity." (PMID 40948778, 2025). "These tumors are characterized by their histological resemblance to prolactin-secreting tumors, yet they do not exhibit the associated hyperprolactinemia or its clinical manifestations." (PMID 41140514, 2025). "One must also be cautious with the interpretation of the prolactin‐adjusted ACTH ratios of these procedures in patients with high prolactin concentrations, as they could potentially be influenced by the presence of hyperprolactinemia." (PMID 40765079, 2025). "Among women with hyperprolactinemia (30 women), 73.4% had tumor etiology (14 women with microadenoma and 8 women with macroadenoma) and 26.6% had idiopatic etiology, 76.7% were using dopamine agonists, and the median of prolactin value was 40.0 ng/mL." (PMID 40406467, 2025). "Two weeks before the endocrinologist appointment, the patient’s PRL levels demonstrated hyperprolactinemia: PRL, 1605 mU/L (reference range: 105–548 mU/L); monomeric PRL, 1150 mU/L (reference range: 74–496 mU/L); and macroprolactin, 151 mU/L (reference range not provided)." (PMID 39928792, 2025). "Considering that normal lactotrophs in patients with NFPAs are very sensitive to dopamine agonists, the use of low-dose cabergoline could completely resolve hyperprolactinemia and even suppress prolactin." (PMID 40960781, 2025). "Hyperprolactinemia is identified as PRL levels exceeding the normal range for the patient’s sex." (PMID 41048428, 2025). "As expected, hyperprolactinemia was more common in patients with GH/PRL positive tumors (54.5% vs. 20.9%, P = 0.011), and the median PRL level was significantly higher in the GH/PRL positive tumors than in the GH positive tumors [22.14 (12.36–91.90) vs. 10.50 (7.12–18.90), P = 0.001]." (PMID 40421250, 2025). "In another series of 36 men with hyperprolactinemia, both the mean testosterone level and the mean hemoglobin level were low, in four cases equal to or less than 11.5 g/dL, and hemoglobin increased after prolactin suppression with cabergoline." (PMID 40621322, 2025). "It is also possible that a rise in prolactin is insidious, and hyperprolactinemia may develop over time, an outcome that our cross-sectional study could not capture." (PMID 40075671, 2025). "Hyperprolactinemia may need to be reversed by switching to prolactin-sparing antipsychotics prior to ART." (PMID 41008479, 2025). "In other pathological conditions with hyperprolactinemia, such as prolactinomas, the relationship of prolactin with cardiovascular disease has also been observed, and therapies that reduce prolactin levels may modify cardiovascular pathology in these patients." (PMID 40650124, 2025). "Likewise, prolactin levels largely overlapped among patients with microprolactinomas, macroprolactinemia, and drug-induced hyperprolactinemia." (PMID 39420933, 2024). "Consequently, there will be a decrease in the dopaminergic inhibitory tone on prolactin secretion, resulting in hyperprolactinemia." (PMID 38578472, 2024). "Therefore, reduction of PRL levels by dopaminergic agonists is essential to prevent metabolic disorders in patients with hyperprolactinaemia." (PMID 39663784, 2024). "In most of the published studies on IGM, however, prolactin levels were not evaluated, and only a minority of published cases have been linked to hyperprolactinemia, e.g., due to antipsychotic medication or intracranial tumors such as pituitary adenomas." (PMID 39410007, 2024).
hyperprolactinemia (continued). "Although macroprolactinemia is the third most frequent cause of hyperprolactinemia, there is still no consensus on routine screening for macroprolactin in patients with elevated prolactin levels." (PMID 39420933, 2024). "In the context of hyperprolactinemia, changes in BMD levels can be triggered either indirectly, through the suppression of the GnRH–gonadal axis caused by elevated prolactin levels, or directly, via prolactin’s influence on osteoblasts and potentially osteoclast cells." (PMID 38338751, 2024). "Only two women had hyperprolactinemia with prolactin levels > 25 μg/L (1.4%)." (PMID 37957366, 2024). "Thus, appropriate treatment of hyperprolactinaemia to restore normal PRL levels in patients with prolactinoma is mandatory therapeutic strategy." (PMID 39663784, 2024). "The impact of prolactin and hyperprolactinaemia on endometriosis-induced infertility has been studied for more than 40 years, but a clear relationship has not been established, even though the association of galactorrhoea and endometriosis was reported for the first time more than 40 years ago." (PMID 39407928, 2024). "The problem of possible connections between hyperprolactinaemia and endometriosis-related infertility is further complicated with the timing of the sampling, which is particularly important for prolactin, as prolactin serum levels have a specific diurnal pattern." (PMID 39407928, 2024). "In nonpregnant IGM women with schizophrenia or bipolar disorder, hyperprolactinemia was secondary to risperidone therapy; however, in some cases, prolactin (PRL) levels may be normal." (PMID 38529282, 2024). "Numerous drugs may increase PRL levels such as antipsychotics which are often responsible for drug‐related hyperprolactinaemia." (PMID 39663784, 2024). "Hyperprolactinemia, an often-undesirable side effect of many antipsychotics, is largely due to the blockade of dopamine D2 receptors, which interrupts the dopaminergic inhibition of the prolactin release." (PMID 38338224, 2024). "Only two women had hyperprolactinemia (prolactin > 25 μg/L; 1.4%)." (PMID 37957366, 2024). "AVP deficiency and hyperprolactinemia may be partially due to thickening of the pituitary stalk, which may have resulted in impairment of AVP and dopamine, a prolactin-suppressing hormone." (PMID 38769570, 2024). "As adenoma size correlates with the degree of hyperprolactinemia, optimal prolactin thresholds that account for the observed gender differences in both serum prolactin levels and adenoma size are warranted to robustly guide and triage these patients for optimal first-line therapy robustly." (PMID 38544490, 2024). "However, it should be noticed that most disturbances of PRL levels post-TBI will manifest as hyperprolactinemia, due to inhibition of transport of PRL inhibitory factor down the pituitary stalk into the gland." (PMID 39172174, 2024). "The hyperprolactinemia in these cases may result from pituitary adenomas cosecreting prolactin and growth hormone (GH) or from compression of the pituitary stalk." (PMID 38578472, 2024). "Disorders of PRL secretion can manifest as either hyperprolactinemia or hypoprolactinemia." (PMID 39172174, 2024). "One possible explanation is that patients with high prolactin levels require continuous administration of DAs to control prolactin levels, and the emotions and behaviors of patients with hyperprolactinemia receiving Das treatment may change." (PMID 38572480, 2024). "About 20% of patients showed mild-to-moderate hyperprolactinemia (PRL > 25 ng/mL)." (PMID 39857650, 2024). "This is consistent with very high PRL levels (> 100 μg/L) observed in patients with prolactinomas and in rodent models of excessive hyperprolactinemia being deleterious for metabolism and with levels within the HomeoFIT-PRL values (< 100 μg/L) being metabolically beneficial." (PMID 38635745, 2024).